Y_RNA (Y RNA )
Gene: Miscellaneous RNA gene on chromosome 1 (23,370,254 to 23,370,346, forward strand). Ensembl gene ENSG00000201405.
Homologues: Orthologues: chimpanzee Y_RNA (99% identical). Paralogues in human: RNY4 (86% identical), Y_RNA (84% identical), RNY4P10 (83% identical), RNY4P6 (83% identical), Y_RNA (83% identical), RNY4P14 (82% identical), RNY4P7 (82% identical), Y_RNA (82% identical), RNY4P17 (81% identical), RNY4P27 (81% identical), Y_RNA (81% identical), RNY4P13 (80% identical), and 87 more.